KRAS (KRas proto-oncogene, GTPase)
Diseases named in the same sentence as KRAS in open-access papers (continued):
Sharing a sentence is not in itself a finding about the gene and the disease.
tumor (continued). "The combination of ABT-263 and NCB-0846 synergistically inhibited KRAS-mutant tumor growth in patient-derived xenograft (PDX) models." (PMID 38275900, 2024). "Tumor heterogeneity and drug resistance are significant difficulties in cancer medicine, especially in KRAS-NSCLC, which is particularly resistant to targeted therapy and first-line chemotherapy." (PMID 38672243, 2024). "The KRAS gene, frequently mutated in MM, is known to activate signaling pathways like MEK/ERK and PI3K/AKT, contributing to tumor cell survival and proliferation." (PMID 39776720, 2024). "Specifically, KIT mutations and KRAS/NRAS mutations have been described as mutually exclusive genetic events in CNS GCTs, meaning they were rarely coexistent within the same tumor." (PMID 38790424, 2024). "Loss-of-function mutations in KEAP1, which account for approximately 20% of KRAS-mutant NSCLC cases, lead to NRF2 activation, resulting in accelerated tumor growth and chemoresistance." (PMID 39037971, 2024). "In tumors with EGFR or KRAS mutation, IK-930, in combination with EGFR or MEK inhibitors, enhanced cell apoptosis and anti-tumor activity in vivo." (PMID 38499647, 2024). "We performed predictive analysis on the downstream target genes regulated by miR-877-5p and found that miR-877-5p can target the oncogene KRAS, exerting a tumor-suppressive function in CC." (PMID 38309290, 2024). "The genetic alterations in oncogenic pathways, such as mutations in genes like EGFR, KRAS, and BRAF, can impact the immune response in the tumor microenvironment." (PMID 39045411, 2024). "EZH2 deletion enhances de novo KRAS-driven neoplasia following pancreatic injury, while increased EZH2 expression in patients with PDAC is correlated to poor prognosis, suggesting a context-dependant effect for EZH2 in PDAC progression." (PMID 39739419, 2024). "KRAS neoantigens can act as a tumor-selective biomarker that can be targeted using engineered T-cells." (PMID 38668053, 2024). "In Ras-driven tumors, YAP can also substitute for oncogenic KRAS to drive tumor survival after the repression of the oncogene." (PMID 39518045, 2024). "KRAS mutation is one of the most prevalent driver mutations in NSCLC, especially the KRAS G12C mutation, which is continuously activated via the RAS-MAPK signaling pathway and promotes the proliferation and survival of tumor cells." (PMID 39640262, 2024). "Other key molecules including MYC, and KRAS in amino acid metabolic signaling pathway are also burgeoning approaches for tumor biotherapy." (PMID 38218942, 2024). "The same study reported that a higher KRAS VAF was associated with a higher frequency of neural/lymphatic invasion, increased tumor cellularity, and decreased inflammatory cellularity." (PMID 38525415, 2024). "To elucidate the insufficient responsiveness of KRAS‐mutant cancers to CDK9i in nude mouse xenograft models, we next investigated the impact of CDK9i on the tumor microenvironment (TME)." (PMID 39254172, 2024). "There, lanosterol uptake by CD8+ T cells suppresses the mevalonate pathway and reduces KRAS protein prenylation and function, which in turn inhibits their activation and establishes a molecular basis for tumor cell immune escape." (PMID 38992029, 2024). "KRAS mutations are frequently observed in many cancers, including BTC, and are linked to tumor growth and therapy resistance." (PMID 39857631, 2024). "It has previously been proposed that wild-type KRAS can exhibit tumour-suppressive characteristics in cancer." (PMID 38168062, 2024). "The vaccine reduced tumor incidence and burden, representing a promising step forward in preventative immunization against KRAS-driven cancers." (PMID 38668053, 2024). "Deletion of RAC1 in a KRAS-driven mouse model of PDAC delayed tumour onset, reduced PanIN lesions, and improved survival." (PMID 38712822, 2024).
tumor (continued). "We conclude that STAT3 Y640F-mediated inhibition of tumor development and KRAS-induced MEF transformation is dependent on STAT3 phosphorylation at Y705, DNA binding, and gene-specific transactivation." (PMID 38573819, 2024). "A contrasting role of KRAS and BRAF mutation on immune cell infiltration in CRC tumours has been previously suggested." (PMID 38040818, 2024). "As expected, we found an enrichment of Myc targets V1 pathway in both Group 3 and Group 4 tumor clones, as well as mTORC1 and KRAS signaling pathways indicating increased proliferative properties in later tumor clones." (PMID 39659836, 2024). "Secretion of AREG-containing EVs by KRAS/PIK3CA mutant CRC cells is also enhanced in response to stressors commonly found in the tumor microenvironment, such as nutrient deprivation and hypoxia." (PMID 40727266, 2024). "Our work provides insights into the effect of KRASG12V degradation on both tumor progression and the immune response, highlighting degraders as a powerful strategy for targeting KRAS-mutant cancers." (PMID 39718828, 2024). "Because KRAS is involved in the RAF/MEK/MAPK and PI3K/PTEN/AKT pathways, these mutations lead to hyperactivated cell division, thereby promoting tumor development and maintenance." (PMID 39698536, 2024). "In KRAS mutant cells, K128 ubiquitination limits tumor growth by restricting RAL/ TBK1 signaling and negatively regulating the autocrine circuit induced by mutant KRAS." (PMID 38858602, 2024). "OAd carrying the tumor suppressor gene miR-143 induces apoptosis and reduces tumor growth by decreasing KRAS expression in HCT116 xenografts." (PMID 39055561, 2024). "In the mouse xenograft model of pancreatic cancer, salirasib and gemcitabine inhibited tumor growth by displacing KRAS from the membrane and influenced the reduction of phosphorylation of MAPK and AKT." (PMID 39056802, 2024). "These engineered chimeric proteins have demonstrated the capability to induce the degradation of KRAS mutants and the cell death in KRAS mutant tumor cell lines." (PMID 39130630, 2024). "In view of the impact of trametinib on PD-L1 expression in tumor cells, we explored the effects of trametinib and anti-PD-1 blockade in two in vivo KRAS-mutant LUAD mouse models." (PMID 38643157, 2024). "Out of 86 tumor samples, 40 (46.5%) harbored somatic mutations within actionable genes (BRAF: 2.3%, KRAS: 43%, NRAS: 2.3%)." (PMID 39635441, 2024). "KRAS G12C mutations occur in 3% to 4% of mCRC patients, driving the tumor’s growth by suppressing the hydrolysis of GTP, which causes KRAS to transition to an active GTP-binding state and activate pro-tumorigenic effector signaling." (PMID 38254903, 2024). "The phase 1 study shows that among 25 patients, 84% exhibited KRAS-specific T cell responses, and 24% observed tumor biomarker clearance." (PMID 39066355, 2024). "They further identified that SLC25A21 dysregulation plays an important role in rewiring tumor metabolism in KRAS-mutant CRC." (PMID 39706835, 2024). "Despite challenges such as resistance mechanisms and tumor heterogeneity, the development of KRAS inhibitors represents a significant advance in CRC treatment and holds promise for improving patient outcomes in the future." (PMID 39456549, 2024). "And we confirmed the results of infiltrated immune cells in tumor tissues from KRAS G12D-mutant patients by IF." (PMID 38402201, 2024). "We determined the role of various KRAS mutations in the prognosis of PDAC patients using biopsy samples and circulating tumor DNA." (PMID 39457426, 2024). "We identified 4 MSI-high samples, 39 KRAS/NRAS mutations, and 5 BRAF p.V600E mutations, with one case of coexistence of all three markers in a single tumor sample." (PMID 38539463, 2024).
tumor (continued). "These macrophages express abundant TGF-β that activates SMAD4 signaling in PDAC cells and enables KRAS-independent tumor growth." (PMID 38167055, 2024). "Sotorasib irreversibly binds the GDP-bound form of KRAS, which stabilizes the protein’s inactive conformation, inhibits tumor cell growth, and promotes apoptosis." (PMID 38610868, 2024). "This compound inhibits ERK activation tumour growth in KRAS G12C pancreatic cell line derived xenograft mice." (PMID 39372214, 2024). "We found that the application of IFNβ OE AAV on KRAS G12D MUT xenografted tumors significantly inhibited tumor growth, volume, and weight." (PMID 39523457, 2024). "Given the dramatic role we have observed in tumour initiation, we next wished to see how important wild-type KRAS would be in tumour progression." (PMID 38168062, 2024). "Several tumors harboring genomic alterations with FDA-approved indications in other tumor types were found including pathogenic PIK3CA, EGFR Exon 19/20 insertions, KRAS G12C (N = 1), FGFR fusions (N = 1), BRAF V600E mutations (N = 4), and BRCA2 (N = 1)." (PMID 39191445, 2024). "Previous work we have performed has suggested a clear role for neutrophils enhancing metastatic progression of KRAS-mutant cancer, across different tumor types." (PMID 38358352, 2024). "While tumor suppressors are still considered to be undruggable, recent developments in the field of KRAS targeting have turned out to be quite promising." (PMID 39632706, 2024). "Given the crucial role of KRAS in modulating anti-tumour immune responses, we determined the anti-tumour activity of RMC-4998 and RMC-4550 in treating tumours formed by transplantation of KPARG12C cells, an immunogenic mouse model of NSCLC26." (PMID 39322643, 2024). "They found that most of the KRAS G12D pancreatic cells (which are tumor drivers) were spontaneously and selectively lost from the pancreatic tissue." (PMID 38607041, 2024). "Previous studies have demonstrated that oncogenic KRAS regulates tumor-intrinsic IFN pathway gene expression." (PMID 38635884, 2024). "Our study analyzed 83 CRC patient tumor tissues from the National Cancer Institute (NCI) database, examining microsatellite instability (MSI), BRAF, KRAS/NRAS mutations, and neoplastic cell percentage." (PMID 38539463, 2024). "Rather, inverse relationships of KRAS VAF with survival outcomes were consistently reported across strata of tumor cellularity levels." (PMID 38525415, 2024). "Results indicated a significant, concentration-dependent reduction in tumor-forming potential of cancer cells expressing oncogenic NRAS, KRAS, and HRAS mutations upon treatment with BAY 11-7092." (PMID 38982514, 2024). "In vivo and in vitro studies demonstrated the enhanced anti-tumor activity from combining mTOR inhibitors, such as everolimus, with KRAS G12C inhibitors." (PMID 38756650, 2024). "They found the KRAS mutation in 39.8% of patients and that the KRAS mutation showed a correlation with the expression of the EGFR gene, primary tumor site, and multiple metastases." (PMID 39125664, 2024). "For example, the KRAS protein released from exosomes of ferroptotic tumor cells can be absorbed by TAMs." (PMID 38475936, 2024). "According to the literature on its molecular mechanism, KRAS activation plays a role in the tumour microenvironment to induce tumorigenesis." (PMID 38087207, 2023).
tumor (continued). "BI-2493 is an in vivo analog of BI-2865 and was found capable of attenuating tumor growth in mice bearing KRAS G12C, G12D, G12V and A146 mutants." (PMID 37925476, 2023). "The anti-tumor activity of tunlametinib as monotherapy was investigated in BRAF/KRAS mutant or wild type xenograft model." (PMID 37808191, 2023). "Herein, we showed that anti-KRAS antibodies can be internalized in the ex vivo cultured matched mucosa-tumor cells." (PMID 37051535, 2023). "The histology of the tumor can also be studied to correlate KRAS internalization and effect on cell viability and KRAS downstream pathway activation." (PMID 37051535, 2023). "The responses of 1-2C and 3-2E TCR-T cells were further tested against varied tumor cells carrying mutant KRAS genes, instead of target cells exogenously loaded with peptides." (PMID 37828002, 2023). "There are other data supporting different lung carcinogenesis behind mutant KRAS variants: G12C mutation is associated with EGFR4 mutation, G12D mutations tend to have PDGRA mutation while G12V mutation containing tumor used to have PTEN mutation." (PMID 38239281, 2023). "Treatment-induced changes in tumor cells included bypassing KRAS inhibition, metabolic reprogramming, and EMT, while changes in the TME consisted of increased coagulation, angiogenesis, and immune suppression." (PMID 36757577, 2023). "It was reported that targeting the α4-α5 dimerization interface using RAS-specific monobody would inhibit oncogenic KRAS and inhibit tumor formation in vivo." (PMID 37110848, 2023). "We assume that most of the c‐cfDNA at baseline was tumor‐derived (similar to KRAS levels), but that with time, it decreased along with a parallel increase in cfDNA from damaged normal intestine (regardless of TRG)." (PMID 36468189, 2023). "iExosomes demonstrated an enhanced ability to target mutant KRAS and resulted in significant tumor reduction in vivo, attributed to CD47-dependent suppression of clearance from circulation and oncogenic KRAS-dependent enhancement of micropinocytosis." (PMID 38069255, 2023). "MTTs are available for very rare mutations, such as for high tumor mutational burden (TMB); however, the molecular landscape of PDAC is dominated by KRAS mutations, the inhibitors of which are pending." (PMID 37761010, 2023). "Conversely, in PBMCs, patients with high KRAS expression were less likely to have a small tumour size." (PMID 36902476, 2023). "Here, we show that an eIF4A inhibitor, which targets a component of eIF4F, dramatically enhances the effects of KRAS G12C inhibitors in NSCLCs and together these agents induce potent tumor regression in vivo." (PMID 37384411, 2023). "Recent studies have indicated that KRAS plays a key role in coordinating tumor metabolic reprogramming by upregulating the transcription of multiple key glycolysis enzymes, such as HK1/2, PFK1, LDHA, and GLUT1." (PMID 36994237, 2023). "In line with this, transwell experiments revealed that tumor‐infiltrating CD8+ T‐cells from fresh CRC tissues with mutant KRAS versus those with wild‐type KRAS had similar migrating abilities." (PMID 36599679, 2023).
tumor (continued). "The width of the resection margins is discussed controversially, especially concerning neoadjuvant chemotherapy, size of the primary tumor and BRAF/KRAS mutation." (PMID 36922643, 2023). "In its mutated form, KRAS remains GTP-bound and, as such, active due to decreased GTP hydrolysis, with increased activity resulting in tumour growth." (PMID 38067288, 2023). "As CIB1 expression was proven to be associated with KRAS mutation and reprogrammed glucose metabolism, a comparison of CIB1 expression between tumor and normal tissues in TCGA cohort revealed that CIB1 was upregulated in PDAC." (PMID 37187730, 2023). "By integrating molecular profiles of a large panel of cell lines from the DEMETER2 dataset, we built a binary classifier to predict a tumor’s KRAS dependency." (PMID 37141389, 2023). "Such a finding is of significant interest considering the remarkable success of PARP1 inhibitors in the clinic and presents a potential new drug target for tumours expressing mutant KRAS, which has hitherto proven difficult to target directly." (PMID 36648336, 2023). "KRAS-comutations have been considered an adverse prognostic factor capable of predicting tumor progression and chemo-resistance." (PMID 37835787, 2023). "Upon repeated intraperitoneal injections in mice with orthotopic PDAC tumors, the exosomes displayed staunch retention in the bloodstream, with effective tumor uptake, reduced KRAS G12D mRNA levels, impaired tumor growth, and improved survival over 30 days." (PMID 37371709, 2023). "CRCs harboring KRAS and BRAF mutations are often refractory to chemotherapy, resulting in a poorer prognosis than cases involving wild-type KRAS and BRAF due to tumor recurrence and metastasis." (PMID 37972012, 2023). "Double-mutant mice with deletion of tumor suppressor PTEN and overexpression of oncogenic KRAS (PR(cre/+)Pten(f/f)Kras(G12D) had severe tumor burden and more invasive cancers than littermates with single mutations." (PMID 37686465, 2023). "We also observed tumor samples with co-occurring driver variants in EGFR, KRAS, and BRAF genes (seven patients with KRAS/EGFR variants; four patients with BRAF/KRAS; one patient with BRAF/EGFR/KRAS)." (PMID 37483495, 2023). "The least concordance rate of KRAS between primary tumor and metastasis was identified by the Badalian G research group, the highest rate being measured by the Rosell R research group and the Alsdorf WH team." (PMID 37345046, 2023). "The chi-square test showed significant differences in tumor location, R0 resection, NLR, CEA, CA19-9, LDH, NLR-LDH values, KRAS mutation with CRLM stage (p < 0.05)." (PMID 37425297, 2023). "In KRAS-mutated CRC, 4HNE linked with MAP kinase and transforming growth factor to inhibit tumor growth." (PMID 36864816, 2023). "To investigate the association between ARGscore and clinical characteristics, we examined the correlation between ARGscore and age, gender, stage, tumor location, BRAF mutation, and KRAS mutation." (PMID 36909170, 2023).